MEP1B (meprin A subunit beta)
Description:
Membrane metallopeptidase that sheds many membrane-bound proteins. Exhibits a strong preference for acidic amino acids at the P1' position. Known substrates include: FGF19, VGFA, IL1B, IL18, procollagen I and III, E-cadherin, KLK7, gastrin, ADAM10, tenascin-C. The presence of several pro-inflammatory cytokine among substrates implicate MEP1B in inflammation. It is also involved in tissue remodeling due to its capability to degrade extracellular matrix components. Also cleaves the amyloid precursor protein/APP, thereby releasing neurotoxic amyloid beta peptides.
Tractability: Small molecule: a structure with a bound ligand is known; a high-quality ligand is known. Antibody: UniProt places it where antibodies can reach, with high confidence; its Gene Ontology location is reachable by antibodies, with high confidence; UniProt predicts a signal peptide or a membrane-spanning region. PROTAC: ubiquitination databases record sites on it; a small molecule that binds it is known.
Target class: Enzyme; Hydrolase
Gene: Protein-coding gene on chromosome 18 (32,185,069 to 32,220,404, forward strand). Ensembl gene ENSG00000141434.
Subcellular location: Cell membrane; Secreted
Gene Ontology:
Molecular function: identical protein binding; protein binding; metalloendopeptidase activity; metallopeptidase activity; zinc ion binding
Biological process: proteolysis
Cellular component: extracellular region; meprin A complex; plasma membrane; membrane
Genetic constraint (gnomAD): Loss-of-function variants: 61 observed, 61.72 expected, observed/expected ratio (o/e) 0.99, 90% interval 0.8 to 1.22. The upper end of that interval is the gene's LOEUF score, 1.22, which puts it in group 5 of 6, group 1 being the genes least tolerant of losing a copy. Missense variants: 664 observed, 756.55 expected, observed/expected ratio (o/e) 0.88, 90% interval 0.82 to 0.94. Synonymous variants: 239 observed, 264.73 expected, observed/expected ratio (o/e) 0.9, 90% interval 0.81 to 1.
Homologues: Orthologues: chimpanzee MEP1B (99% identical), macaque MEP1B (94% identical), dog MEP1B (85% identical), rabbit MEP1B (84% identical), guinea pig MEP1B (80% identical), pig MEP1B (80% identical), mouse Mep1b (78% identical), rat Mep1b (76% identical), tropical clawed frog mep1b (62% identical), zebrafish mep1bb (58% identical), zebrafish mep1ba (53% identical). Paralogues in human: MEP1A (42% identical), TLL2 (19% identical), BMP1 (18% identical), TLL1 (18% identical), CUBN (17% identical), CNTNAP3 (15% identical), CNTNAP3B (15% identical), CNTNAP4 (15% identical), F5 (15% identical), CNTNAP2 (14% identical), ASTL (14% identical), F8 (14% identical), and 23 more.
Diseases named in the same sentence as MEP1B in open-access papers:
MEP1B is named in the same sentence as 17 diseases in open-access papers, as found by Europe PMC text mining. Sharing a sentence is not in itself a finding about the gene and the disease. The quoted sentences say what the papers report.
diabetic kidney disease (3 papers, 2018 to 2022). Progressive kidney disorder caused by vascular damage to the glomerular capillaries, in patients with diabetes mellitus. "Based on the results of transcriptomics, the pathogenesis of diabetic kidney disease may involve 11 candidate differential genes: Egr1, Foxo3, Pik3r3, Fgf1, Sost, Wnt10a, Tgif2, Akt2, Mep1b, Col1a1, Apoe." (PMID 36249745, 2022).
chronic kidney disease (1 paper, 2023). Impairment of the renal function secondary to chronic kidney damage persisting for three or more months. "Ghr has been previously associated with chronic kidney disease, whereas Mep1b plays a role in acute kidney injury, with Mep1b−/− mice showing improved renal function compared to WT mice." (PMID 37275529, 2023).
dementia (1 paper, 2022). Loss of intellectual abilities interfering with an individual's social and occupational functions. "Of note, the potential relevance for meprin β in AD was recently supported by a genetic study where a Mep1b variant was identified as one of the AD-associated genes in a British dementia cohort." (PMID 35235058, 2022).
diabetes (1 paper, 2009). "Finally, altered renal transcription of Rbp1 and Mep1b has been reported in mouse models of experimentally-induced diabetes and tubular fibrosis." (PMID 19586551, 2009).
melanoma (1 paper, 2021). A malignant, usually aggressive tumor composed of atypical, neoplastic melanocytes. "Searching the BioMuta database, several single nucleotide variants (SNVs) of the Mep1b gene can be found in different cancer entities identified by multiple genomic studies, with the largest number identified in melanoma, uterine cancer, and lung cancer." (PMID 34692768, 2021).
Nephropathy (1 paper, 2014). A nonspecific term referring to disease or damage of the kidneys. "Moreover, the level of Mep1b expression is inversely related to the severity of nephropathy in diabetic mice." (PMID 24827579, 2014).
tumor (2 papers, 2022 to 2025). "Surprisingly, in this study, the RNA-seq analysis revealed an increase of mep1b gene expression, which, as reported in several studies, should be associated with an increase of cytokines by the leukocyte influx promotion and tumor cell migration." (PMID 36564370, 2022). "Through bioinformatic analysis, we identified four MAM domain-containing genes (EGFL6, MEP1A, MEP1B, and MAMDC2) that showed significant differential expression between tumor and adjacent normal tissues in CRC." (PMID 40427044, 2025).
MEP1B also shares sentences with these, for which no sentence is quoted: cancer (2 papers); kidney disease (2); Alzheimer disease (1); colon cancer (1); heart failure (1); infection (1); inflammatory bowel disease (1); kidney (1); nutritional deficiency (1); Salmonella Infections (1).